MPDU1-AS1 (MPDU1 antisense RNA 1)
Synonyms: AC016876.1
Gene: Long non-coding RNA gene on chromosome 17 (7,581,960 to 7,584,102, reverse strand). Ensembl gene ENSG00000233223.
Diseases named in the same sentence as MPDU1-AS1 in open-access papers:
MPDU1-AS1 is named in the same sentence as 4 diseases in open-access papers, as found by Europe PMC text mining. Sharing a sentence is not in itself a finding about the gene and the disease.
MPDU1-AS1 shares sentences with these, for which no sentence is quoted: breast carcinoma (1 paper); cancer (1); colorectal cancer (1); non-small cell lung carcinoma (1).